MITF (melanocyte inducing transcription factor)
Diseases named in the same sentence as MITF in open-access papers (continued):
Sharing a sentence is not in itself a finding about the gene and the disease.
melanoma (continued). "In summary, it can be stated that the addition of RGD-apoptins to melanoma cells does not significantly affect MITF expression, yet it successfully overcomes the pro-survival effect regulated by this transcription factor." (PMID 41465443, 2025). "While this aberration is less locus-specific than the MITF amplification, BRAF is a well-described melanoma oncogene and thus this amplification could have also contributed to the progression of the disease." (PMID 41168392, 2025). "MITF seems to be sensitive and specific to epithelioid melanomas, but not for spindle cell and desmoplastic melanomas, with studies reporting 1–3% of desmoplastic melanomas as being MITF-positive." (PMID 40507250, 2025). "Our results suggest that MITF+ melanoma cells are efficiently targeted by immunotherapy, while AXL+ melanoma cells may be more resistant." (PMID 39697983, 2024). "The addicted Melanoma cells experienced grave cell death upon withdrawal from BRAFi, which could be rescued by ERK2 targeting or restoring MITF activity." (PMID 38485987, 2024). "Next, we investigated the MITF and BRN2 protein levels in quiescent melanoma cells printed in CIB." (PMID 38773108, 2024). "On the other hand, it has also been reported that MITF expression in melanoma induces NK cell cytotoxicity by inhibiting integrin beta-like protein 1 (ITGBL1) expression, which is increased in MITF-low melanoma cells and in patients with resistance to anti-PD1 therapy." (PMID 38351314, 2024). "A375 cells are acknowledged to be a particularly invasive and aggressive type of melanoma that is MITF-negative and AXL-enriched." (PMID 39596498, 2024). "In addition, MITF knockdown by siRNA reduced the expression of HVEM in melanoma cell lines and patient-derived melanoma cells." (PMID 38351314, 2024). "Whereas the interplay between MITF and individual redox genes such as HIF1α18, PGC1α19, and APEX121 has been shown before, our study revealed the extent of how deeply MITF is involved in the redox metabolism of human melanoma." (PMID 39277608, 2024). "Thus, HIF-1α can indirectly, via EMT induction, or directly via MITF/AXL expression, shift melanoma phenotypes towards immunosuppressive and metastatically-inclined states." (PMID 38426087, 2024). "Treatment with α-melanocyte-stimulating hormone (α-MSH; 150 nM) increased the melanin content of melanoma cells as well as the expression of melanogenic proteins, namely MITF, TYR, and TRP-1,2 compared with that in the negative control (p < 0.05)." (PMID 38338991, 2024). "We investigated the distribution of MET expression and of Ecad (CDH1) and MITF, the transcriptional regulator of MET in melanocytes as well as marker of pigmented melanoma cells among primary tumors, extracranial metastases (TCGA-SKCM), and brain metastases (MBM_CHA)." (PMID 38386085, 2024). "Consistent with the negative correlation between the AXL and MITF transcriptional programs in melanoma, we observed an inverse expression pattern between AXL and MITF." (PMID 39697983, 2024). "Among the downregulated genes known to play an important role in melanoma progression are CXCL1, which exerts melanoma growth-stimulating activity, and MITF, a crucial oncogenic transcription factor to maintain tumor survival, increase proliferation, and promote differentiation." (PMID 39339213, 2024). "We also found a negative correlation between the proportion of MITF+ melanoma cells and CD8+ T-cell infiltration in the tumor tissue." (PMID 39697983, 2024). "mIF did not reveal any correlation between the proportion of AXL or MITF melanoma cell phenotypes and the density of leukocyte infiltration, as identified by CD45 expression (not shown)." (PMID 39697983, 2024). "Moreover, the expression of TYR, MITF, EDNRB, and TRP-1/2 was elevated again when rosiglitazone and GW acted together on melanoma cells, as PPAR-γ was activated." (PMID 38159176, 2024).
melanoma (continued). "This phenotype may also occur in melanoma, where miRNA-mediated changes in HIF-1α and MITF expression have been reported." (PMID 39594467, 2024). "Four other melanoma cell lines do not increase PD-L1 mRNA expression following MITF knockdown and IFNγ treatment." (PMID 39736644, 2024). "It is unclear whether the paradoxical effect of CREB on melanoma aggressiveness involves MITF, a CREB-responsive gene that inhibits melanoma invasiveness." (PMID 38233872, 2024). "Our findings are consistent with previous reports identifying MITF and AP-1/TEADs as regulators of the proliferative and invasive cellular states in melanoma, while recognizing some novel TF genes that have not previously been linked to these processes." (PMID 38319712, 2024). "Altogether these data suggest that the impact of miR-579-3p on senescence programs are not dependent from MITF in BRAF-mutant melanoma cells." (PMID 38472212, 2024). "To examine how this increase in ROS affects the survival of melanoma cells, we measured the viability of UACC257 melanoma cells upon MITF, NNT, or IDH1 knockdown in the presence or absence of the thiol antioxidant N-Acetyl-L-Cysteine (NAC)." (PMID 39277608, 2024). "Other markers beyond MITF and AXL can give insight to melanoma phenotypes produced by EMT." (PMID 38426087, 2024). "In addition to MITF, transcription factor EB (TFEB), another member of the MiT transcription factor family, has been suggested to play a role in melanoma onset and progression." (PMID 37160873, 2023). "For example, while MITF amplification is found in 15%–20% of human metastatic melanomas with poor prognosis, deep sequencing has detected no sign of alteration in MITF copy number in patient-derived melanoma metastases." (PMID 38020918, 2023). "The compound also inhibited MITF (melanocyte inducing transcription factor) in the B16-F10 melanoma cell line, the factor that not only regulates melanin production, but is also responsible for cell cycle control, proliferation, survival and migration." (PMID 38067491, 2023). "Molecular studies of melanoma cells with absent SOX10 showed reduced expression of MITF, elevated expression of p21/WAF1 and p27KIP2, hypophosphorylated RB, and reduced levels of E2F1." (PMID 38132479, 2023). "We observed distinct melanoma cell responses to T cell challenge: whereas several cell lines showed downregulation of MITF, others failed to diminish its expression." (PMID 36812891, 2023). "UM cells are commonly stained with melanocytic differentiation markers such as S-100, human melanoma black 45 (HMB45), melan-A/melanoma antigen recognized by T cells 1 (MART-1), melanocyte-inducing transcription factor (MITF) and sex-determining region Y-box 10 (SOX10)." (PMID 36765733, 2023). "Melan-A, MITF, andHMB45 can aid in distinguishing MPNST from carcinomas and melanomas." (PMID 36831419, 2023). "EZH2 knockout by CRISPR-Cas9 induced MITF in pigmented melanoma cell lines (28:B4:F3 and C006-M1), but not in non-pigmented SK-MEL-28 and A375 cells." (PMID 36906655, 2023). "Thus, as well as MITF, GREB1 is expressed in benign nevi and tumor lesions of melanoma and their expression is correlated in both inter- and intra-tumors, and it is likely that GREB1 expression in tumor lesions is associated with aggressiveness of melanoma." (PMID 37658191, 2023). "Among them, the MITF gene and its targets were found to be down-regulated in the MES-like group, while down-regulation was observed in the representative MES-like genes, validating the results of melanoma cell state clustering." (PMID 36765773, 2023). "In addition to MITF, we screened several potential molecules that mainly affect certain melanoma characteristics, including RAS, MITF, PI3K, NF-κB, and STAT3." (PMID 37575275, 2023).
melanoma (continued). "The MITF and SOX10 genes play roles as master regulators of melanocyte and melanoma development." (PMID 36251678, 2023). "Overexpressing AR in melanoma A375 and WM115 cells significantly decreases MITF protein levels." (PMID 37070131, 2023). "A total of 195 TFs were predicted to be under the regulation of these elements including major, already established transcriptional dependency of melanoma (SOX10 and MITF) or factors like SNAI1 and SNAI2 that drive the transition toward the mesenchymal phenotype." (PMID 37408506, 2023). "Apparently, patients with positive androgen receptors have a worse survival as opposed to melanoma patients with negative androgen receptors, as they also promote melanoma metastases through MITF signaling." (PMID 36676131, 2023). "Consistently, M-stiff melanoma cells downregulated MITF upon seeding in soft gels, in which H-stiff cells did not alter the high expression of MITF." (PMID 37614365, 2023). "Finally, recent research paper has depicted EZH2 as a key regulator of pigmentation and melanoma plasticity, since EZH2 expression negatively correlates with melanocyte inducing transcription factor (MITF)." (PMID 37325482, 2023). "Interestingly, the PI3K-Akt signaling pathway shared all genes enriched in melanoma pathway (e.g., CDK6, FGF20, and MITF) and included three additional genes (i.e., RPTOR, COMP, and CDC37), suggesting a higher level of significance and potential relevance." (PMID 37829282, 2023). "Consistent with the downregulation of melanogenesis-related genes, ablation of TG2 leads to a reduction of MITF mRNA levels, both in B16F10 melanoma TG2 KO clones, as well as in human melanoma cell lines Mel JuSo, IPC-298 and SK-MEL-3 following downregulation of TG2 by siRNA." (PMID 37898636, 2023). "We observed that melanoma cells in patients responding to treatment had significantly lower levels of MITF and MITF target genes than prior to treatment or non-responders." (PMID 36812891, 2023). "Very low or absent expression of MITF is characteristic of invasive melanoma cells, while high expression of MITF characterizes non-invasive melanoma cells." (PMID 36675114, 2023). "Indeed, MITF and GREB1 Is4 were co-expressed in melanocytic melanoma cells lines and in 40% of benign nevi, and 20% of melanoma tumors." (PMID 37658191, 2023). "The same germline MITF PV was found in another patient (#62) with BRAF V600+ melanoma non-responding to both first-line and second-line therapies with TT and ICI agents, respectively." (PMID 36901733, 2023). "In addition, Biomarkers such as S100 protein, micropthlamia transcription factor (MITF), tyrosinase and SOX10 are also widely used in the diagnosis of melanoma." (PMID 37427124, 2023). "In melanoma cells, where DIRC3 is highly expressed, DIRC3 increases IGFBP5 transcription by preventing the TFs SRY-Box transcription factor 10 (Sox10) and melanocyte inducing transcription factor (MITF) from inhibiting IGFBP5 transcription." (PMID 36093095, 2022). "Paradoxically, the absence of endogenous MITF expression has also been be associated with MAPK inhibitor resistance, suggesting that either the excess or absence of MITF is permissive for cell viability under decreased MAPK signaling in BRAF-mutant melanoma." (PMID 35580987, 2022). "Since both SOX10 and MITF have fundamental roles in developing melanocytes and in melanoma progression, depletion of SOX10 in an MITFlo background resulted in high lethality for most of the melanoma cell cultures tested." (PMID 36040798, 2022). "We have previously demonstrated that melanoma persister cells in the MRD site do not express Mitfa protein (called MITF independent), but maintain a neural crest identity and express Sox10." (PMID 35929478, 2022). "Additionally, both tyrosinase agonist 2-ETZ and tyrosinase substrate L-tyrosine significantly increased MITF, Tyrosinase, TYRP1 and TYRP2 expression and tyrosinase activity in parental B16 melanoma cells." (PMID 35265199, 2022).
melanoma (continued). "In conclusion, melanoma cells lacking the melanocyte transcription factor MITF can be divided based on SOX10 mRNA levels." (PMID 36040798, 2022). "Notably, in all human melanoma studies reported in cBioPortal, there is a significant positive correlation between DUSP4 and MITF mRNA expression." (PMID 35580987, 2022). "In the same study, the authors show that MITF can repress its own expression by a negative feedback loop and that melanoma cells with distinct phenotypes display different responses to hypoxia." (PMID 35406721, 2022). "Although the genomic evolution of metastasis in CM is not as clear as in other melanoma subtypes, several studies reinforce the idea that mutations in EGFR4 and NMDAR2, amplifications of MITF and MET, and loss of PTEN can be regarded as metastasis drivers." (PMID 36143375, 2022). "Indeed, we found a significant time-dependent Cpd1-induced transcription of the melanocytic master regulator MITF and other downstream differentiation genes like DCT, TYR, and MART-1/MLANA in pigmentation-competent melanoma cells." (PMID 35650266, 2022). "Moreover, a recent RNA-sequencing analysis conducted on SkMel-28 melanoma cells reveals a significant downregulation of SEMA6A following MITF knock out, suggesting the possible involvement of MITF in BRAFV600E-driven regulation of SEMA6A." (PMID 35440004, 2022). "Moreover, expression of both MITF and BRN2 proved indispensable for melanoma to efficiently metastasise." (PMID 35740696, 2022). "Additionally, TAMs secrete TNFα, which promotes MITF expression and inhibits BRAF protein to block apoptosis in melanoma." (PMID 36181568, 2022). "In order to discern the role of SOX10 in determining the aggressive phenotype of MITF-methylated melanoma, we specifically targeted SOX10 by CRISPR/Cas9 to generate a SOX10 knockout (SOX10KO) MITF-methylated melanoma cell line with SOX10-unmethylated promoter CpGs." (PMID 36040798, 2022). "It would appear to be difficult to target β-catenin in melanoma without affecting MITF expression and/or activity." (PMID 35158973, 2022). "Interacts with MITF and SOX10 in melanocytes and melanoma cells." (PMID 35323214, 2022). "However, inhibition of MC1R in normal melanocytes and melanoma cells was observed to trigger PI3K/Akt and MAPK/ERK pathways, leading to inhibition of MITF and subsequent suppression of melanogenesis." (PMID 35645796, 2022). "Depletion of USP13 in MITF-positive melanoma cells reduces MITF protein levels without affecting MITF mRNA levels through regulation of its ubiquitination state and the subsequent increase in MITF proteasome-mediated degradation." (PMID 35884430, 2022). "MITF expression levels are important but by far not the only criterion in physiology and pathology of melanocytes and melanoma cells." (PMID 35682684, 2022). "In B16 melanoma cells, they increase the intracellular cAMP level and PKA activity, translating to increased phosphorylation of CREB, its downstream signaling protein, followed by up-regulation of MITF and TYR expression." (PMID 35889231, 2022). "However, in contrast to the “MITF-low” GES, melanoma cells with the “EMT” GES showed high expression levels of EMT-TFs (ZEB1, SNAI1, and PRRX1), which have been demonstrated to play a critical role in melanoma progression." (PMID 35884783, 2022). "Currently, at least seven in vivo melanoma phenotypes have been characterized by low to high MITF activity: undifferentiated (mesenchymal-like), neural crest stem cell-like (NCSC), interferon-active (IFN-active), starved melanoma cells (SMCs), intermediate, melanocytic, and hyper-differentiated." (PMID 36497341, 2022).
melanoma (continued). "Immunohistochemical staining shows a positive reaction to melanoma‐associated markers such as SOX10, HMB‐45, HMB‐50, Melan A, MITF, and NKI‐C3 and myogenic markers like SMA, but not to epithelial markers such as cytokeratin." (PMID 36056704, 2022). "Additionally, MITF and BRN2-expressing cells act jointly in melanoma progression by first stimulating tumour growth with MITFhigh cells and then activating tumour invasion with BRN2high cells." (PMID 35740696, 2022). "MITF belongs to the helix-loop-helix leucine zipper (b-HLH-zip) family, the functions of which have been investigated in-depth in the development and maintenance of melanoma." (PMID 35957803, 2022). "Another gene that is able to repress MITF is BRN2, which mediates melanoma cell invasion." (PMID 35682684, 2022). "Moreover, it has been documented that long non-coding RNA (lncRNA) SAMMSON, which co-expresses with MITF, promotes melanoma growth by upregulating mitochondrial main regulatory factor p32 and targeting SAMMSON renders melanoma cells therapeutic vulnerability." (PMID 36003368, 2022). "In this context, melanoma cell lines display strong melanocytic features, such as upregulation of melanocytic antigens MART-1 (also known as MLANA) and gp100 (also known as PMEL) and increase in MITF expression." (PMID 36551603, 2022). "Phosphorylation at MITF Ser73 is predominantly responsible for MITF activation to promote malignant phenotypes in melanoma; however, this interaction has not been reported in GC." (PMID 36268034, 2022). "To investigate the clinical relevance of such findings, we analyzed MITF protein expression by immunostaining of a melanoma tissue microarray including 177 metastases and found 17% of these cases to be MITF negative." (PMID 36040798, 2022). "The 15 negative conventional pan-melanoma-cocktail cases were represented by 9 cases with SOX11/SOX10/MITF triple positivity, 4 cases expressing only SOX10 positivity, and 2 cases that expressed HMB-45 and melan-A." (PMID 33801642, 2021). "Although Müller and colleagues reported an inverse correlation between AXL and MITF levels in drug-resistant melanoma, drug resistance is not exclusively determined by AXLhigh/MITFlow phenotype." (PMID 33800547, 2021). "The upregulation of AXL occurred predominantly in the transitory and dedifferentiated melanomas, suggesting that although MITF and AXL expression has been reported to be inversely correlated in melanoma, their regulation by TNFα appear dependent on variable mediators." (PMID 34073253, 2021). "miR-340, which was first identified in melanoma cell lines for its ability to bind specifically to the 3′-UTR of MITF, has been also investigated in immortalized human epidermal melanocytes (Pig-1), where it downregulates MITF expression and melanin synthesis." (PMID 34198907, 2021). "However, while elevated susceptibility to NK-mediated killing was a characteristic of both MITF-KO and ADAM10-KO melanoma cells, a major difference was observed when we performed a vaccination assay." (PMID 33789714, 2021). "Here we show that SALL4 can build a protein complex together with HDAC2 also in human melanoma cells and that SALL4 and HDAC2 together directly bind to genes involved in melanocyte and melanoma biology, such as VEGFR-1, CDH2 (N-cadherin), FN1, TGFBR2, MITF, and others." (PMID 34417458, 2021). "Mutually exclusive expression of MITF and BRN2 was identified in patient melanomas and xenografts." (PMID 34604096, 2021).